LYST (lysosomal trafficking regulator)
Description:
Adapter protein that regulates and/or fission of intracellular vesicles such as lysosomes. Might regulate trafficking of effectors involved in exocytosis. In cytotoxic T-cells and natural killer (NK) cells, has role in the regulation of size, number and exocytosis of lytic granules. In macrophages and dendritic cells, regulates phagosome maturation by controlling the conversion of early phagosomal compartments into late phagosomes (By similarity). In macrophages and dendritic cells, specifically involved in TLR3- and TLR4-induced production of pro-inflammatory cytokines by regulating the endosomal TLR3-TICAM1/TRIF and TLR4-TICAM1/TRIF signaling pathways.
Synonyms: CHS; CHS1; Mauve
Tractability: PROTAC: ubiquitination databases record sites on it; its protein half-life has been measured.
Gene: Protein-coding gene on chromosome 1 (235,661,041 to 235,883,724, reverse strand). Ensembl gene ENSG00000143669.
Subcellular location: Cytoplasm
Subcellular location (Human Protein Atlas): Nucleoplasm; Centriolar satellite; Plasma membrane
Gene Ontology:
Molecular function: protein binding
Biological process: endosome to lysosome transport via multivesicular body sorting pathway; natural killer cell mediated cytotoxicity; pigmentation; defense response to bacterium; defense response to protozoan; defense response to virus; leukocyte chemotaxis; lysosome organization; mast cell secretory granule organization; melanosome organization; defense response to other organism; immune response; lymphocyte mediated immunity
Cellular component: microtubule cytoskeleton; nucleoplasm; lysosome; cytoplasm
Genetic constraint (gnomAD): Loss-of-function variants: 137 observed, 312.8 expected, observed/expected ratio (o/e) 0.44, 90% interval 0.38 to 0.5. The upper end of that interval is the gene's LOEUF score, 0.5, which puts it in group 2 of 6, group 1 being the genes least tolerant of losing a copy. Missense variants: 3,167 observed, 3,866 expected, observed/expected ratio (o/e) 0.82, 90% interval 0.8 to 0.84. Synonymous variants: 1,245 observed, 1,373.5 expected, observed/expected ratio (o/e) 0.91, 90% interval 0.86 to 0.95.
Gene-disease validity (ClinGen):
ClinGen rates the evidence that LYST causes each of these diseases.
Chediak-Higashi syndrome (autosomal recessive): Definitive.
Homologues: Orthologues: chimpanzee LYST (99% identical), macaque LYST (97% identical), rabbit LYST (91% identical), dog LYST (91% identical), pig LYST (90% identical), guinea pig LYST (86% identical), rat Lyst (86% identical), mouse Lyst (85% identical), tropical clawed frog lyst (63% identical), zebrafish lyst (44% identical). Paralogues in human: WDFY3 (17% identical), WDFY4 (17% identical), NBEAL1 (14% identical), NBEAL2 (13% identical), NBEA (12% identical), LRBA (11% identical), NSMAF (6% identical).
Diseases named in the same sentence as LYST in open-access papers:
LYST is named in the same sentence as 91 diseases in open-access papers, as found by Europe PMC text mining. Sharing a sentence is not in itself a finding about the gene and the disease. The quoted sentences say what the papers report.
Chediak-Higashi syndrome (64 papers, 2007 to 2025). ChC)diak-Higashi syndrome (CHS) is a rare severe genetic disorder generally characterized by partial oculocutaneous albinism (OCA), severe immunodeficiency, mild bleeding, neurological dysfunction and lymphoproliferative disorder. "Mutations in the human LYST gene have been implicated in different diseases, most notably the autosomal recessive immunodeficiency disease Chediak-Higashi syndrome, marked by enlarged lysosomes and LROs." (PMID 40315422, 2025). "Pakistani Punjabis: LYST mutations (Chediak-Higashi syndrome) were elevated in consanguineous families." (PMID 40898550, 2025). "Chediak–Higashi syndrome (OMIM #214500) is a rare autosomal recessive genetic disorder caused by biallelic mutations in the Lysosomal Trafficking Regulator gene (LYST, 1q42.3, OMIM *606897)." (PMID 39858566, 2024). "In this study, we report two novel heterozygous variants in the coding region of the LYST gene in an individual with a clinical presentation of Chediak–Higashi syndrome and demonstrate an abnormal splicing signature in both variants’ cases." (PMID 39858566, 2024). "Chediak–Higashi syndrome (CHS) is a genetic disorder resulting from mutations in the lysosomal trafficking regulator gene (CHS1/LYST)." (PMID 39329678, 2024). "Chediak–Higashi syndrome is a rare autosomal disorder characterized by large lysosomal granules in granulocytes caused by mutations in the lysosomal trafficking regulator (LYST) gene." (PMID 35329073, 2022). "LAMP1 is associated with Lysosomal Trafficking Regulator (LYST), which causes the multi-system Chediak-Higashi Syndrome." (PMID 33630878, 2021). "investigate the role of Mauve, the Drosophila homolog of the gene LYST, which is mutated in the poorly understood Chediak-Higashi syndrome." (PMID 33725482, 2021). "Chediak–Higashi syndrome, which manifests as albinism, excessive bleeding and immunodeficiency, is caused by mutations in lysosomal trafficking regulator (LYST), which appears to function in endolysosomal trafficking." (PMID 32433026, 2020). "Chediak-Higashi Syndrome is a well-characterized lysosomal disease caused by mutations in lysosomal trafficking regulator (LYST)." (PMID 31919397, 2020). "On the other hand, LYST (1q42) mutation is the cause of Chediak-Higashi Syndrome (CHS) and is involved in vesicle trafficking." (PMID 30782130, 2019). "Many researchers have reported that the gene LYST is associated with Chediak-Higashi syndrome, which can affect many parts of the body, particularly the immune system." (PMID 31332212, 2019). "Paternal heterodisomy in chromosome 1 involving the LYST (lysosomal trafficking regulator) gene containing a substitution introducing a stop codon on RNA causes Chediak-Higashi syndrome." (PMID 30591019, 2018). "Chediak–Higashi syndrome (CHS) is an AR disorder caused by defects in LYST leading to defects in granule morphogenesis with delayed and incomplete degranulation." (PMID 28894446, 2017). "LYST (lysosomal trafficking regulator) is mutated in Chédiak-Higashi syndrome and the beige mouse (the acronym BEACH is derived from “beige and Chédiak-Higashi”)." (PMID 28814779, 2017). "Chediak–Higashi syndrome (CHS) is caused by autosomal recessive mutations in LYST, resulting in enlarged lysosomal compartments in multiple cell types." (PMID 28458669, 2017). "Chediak-Higashi syndrome is caused by a mutation in the LYST gene, which encodes a lysosomal trafficking regulator." (PMID 27005275, 2016). "For example, defects in LYST are associated with the rare autosomal recessively inherited Chediak–Higashi syndrome, while platelet P2Y12 receptor deficiency is usually due to recessive inheritance of P2RY12 defects." (PMID 25556537, 2015). "Mutations in the CHS1 gene (also known as LYST) have been found to be connected with Chédiak-Higashi syndrome." (PMID 25093188, 2014).
Chediak-Higashi syndrome (continued). "Chediak–Higashi syndrome, a mutation of the lysosomal trafficking regulator (LYST) causes the formation of giant granules in many cells including MC, and can be studied using the orthologous lyst-deficient beige (Lystbg/Lystbg) mouse." (PMID 25452755, 2014). "Griscelli syndrome type 2 is identified by mutations in RAB27A while Chediak Higashi syndrome is associated with LYST mutations." (PMID 22554126, 2012). "Patients with Chediak-Higashi syndrome have biallelic mutations of the gene encoding the cytoplasmic protein lysosomal trafficking regulator (LYST;OMIM*606897) and have granulated cells with giant intracytoplasmic lysosomal structures." (PMID 22970278, 2012). "LYST is a large cytosolic protein that influences the biogenesis of lysosome-related organelles, and mutation of the encoding gene, LYST, can cause Chediak-Higashi syndrome." (PMID 20617205, 2010). "Mutations in the encoding gene, LYST, can cause Chediak-Higashi syndrome, a rare, autosomal recessive disorder characterized by variable degrees of oculocutaneous albinism, immunodeficiency, prolonged bleeding time, and progressive neurologic dysfunction." (PMID 20617205, 2010). "This first Moroccan report of five cases of Chediak-Higashi syndrome highlights the diagnostic utility of cytology, particularly through the identification of pathognomonic giant granules, in settings with limited access to LYST gene analysis." (PMID 40704228, 2025). "In addition, mutations affecting LYST in humans cause the Chédiak–Higashi syndrome, characterized by oculocutaneous albinism and immunodeficiency." (PMID 33020272, 2020). ", LYST is associated with lung cancer, malignant melanoma, and Chediak-Higashi syndrome." (PMID 31332212, 2019). "Similarly, Lyst encodes the lysosomal trafficking regulator protein which is important for trafficking components to the early stage 1 melanosomes, and variants can cause Chediak-Higashi syndrome (number 214500)." (PMID 29780638, 2018). "Mutations in LYST, a gene encoding a putative lysosomal trafficking protein, cause Chédiak-Higashi syndrome (CHS), an autosomal recessive disorder typically characterized by infantile-onset hemophagocytic syndrome and immunodeficiency, and oculocutaneous albinism." (PMID 23521865, 2013). "Autosomal recessive Chediak-Higashi syndrome (CHS) results from a mutation in the lysosomal trafficking regulator (LYST) or CHS1 gene and leads to partial albinism, neurological abnormalities, and recurrent bacterial infections." (PMID 33725482, 2021). "Biallelic LOF mutations in LYST underlie Chediak-Higashi syndrome (CHS), a rare inherited immune disorder in which patients can develop the signs and symptoms of HLH." (PMID 34868048, 2021). "Chediak-Higashi syndrome (CHS) is a rare disorder caused by biallelic mutations in the lysosomal trafficking regulator gene (LYST), resulting in formation of giant lysosomes or lysosome-related organelles in several cell types." (PMID 29241728, 2018). "Rare patients with Chediak–Higashi syndrome (caused by mutations in the lysosomal trafficking regulator LYST gene) may also present with spastic paraplegia, cerebellar ataxia and peripheral neuropathy, without the hypopigmentary or immune deficiency typically associated with this condition." (PMID 25480570, 2015). "Chediak-Higashi syndrome (CHS) is an autosomal recessive disorder caused by mutations in the Lysosomal Trafficking Regulator (LYST) gene, which lead to a broad range of clinical manifestations associated with the enlargement of lysosomes and LROs, including MC SGs." (PMID 40486912, 2025). "Chediak-Higashi syndrome (CHS) is a rare, autosomal recessive disorder caused by pathogenic variants in the lysosomal trafficking regulator (LYST) gene and characterized by significant immunological and neurological impairment." (PMID 40681653, 2025).
Chediak-Higashi syndrome (continued). "The preliminary diagnoses for cases with newly identified LYST variations c.10699C > T (p.Gln3567Ter) and c.10423 T > C (p.Ser3475Pro) were Chediak-Higashi syndrome." (PMID 38644452, 2024). "Lysosomal trafficking regulator (LYST) is a member of the Beige and Chediak-Higashi syndrome (BEACH) family, which regulates the transport of vesicles to lysosomes and regulates TLR signaling pathway, but the effect of LYST on C. burnetii infection is unclear." (PMID 38282619, 2023). "Lysosomal transport regulatory factor (LYST) is a highly conserved homologous protein in mammals, which is classified as a member of the Beige and Chediak-Higashi syndrome (BEACH) family due to a special BEACH region." (PMID 38282619, 2023). "LYST gene is the responsible for Chediak-Higashi syndrome, an autosomal recessive bleeding disorder with coat color dilution in Japanese Black cattle, and Arg allele of p.His2015Arg leads its onset." (PMID 36207673, 2022). "Chediak-Higashi Syndrome (CHS) is a well-characterized, autosomal recessively inherited lysosomal disease caused by mutations in lysosomal trafficking regulator (LYST)." (PMID 31919397, 2020). "Griscelli syndrome type 2 (GS2) and Chediak-Higashi syndrome (CHS), caused by mutations in RAB27A and LYST, respectively, are also associated with development of HLH." (PMID 27413758, 2016). "LYST (lysosomal trafficking regulator, also known as CHS1) is the causal gene for Chediak-Higashi syndrome, an inherited immunodeficiency disease, and CHM (Rab escort protein 1) is responsible for an inherited human retinal blindness known as choroideremia." (PMID 17915034, 2007). "In contrast, DNA-RD-negative patients included 10 (58.8%) patients with familial MPNs, 4(23.5%) with DC, 2(11.8%) with Chediak-Higashi syndrome due to homozygous variant in LYST gene, and one (5.8%) patient without an identified genetic cause by WES." (PMID 40047910, 2025). "Additionally, mutations in Lysosomal trafficking regulator (LYST), which we found to be strongly phosphorylated at 30 min post DMXAA treatment (Fig EV2C) are causative in an immunodeficiency disease known as Chediak‐Higashi syndrome (CHS)." (PMID 37139896, 2023). "Primary HLH can be caused by mutations in a number of genes which affect cytotoxic lymphocyte granule-mediated cytotoxicity including PRF1, UNC13D, STX11, STXBP2, RAB27A (Griscelli Syndrome), AP3B1 (Hermansky-Pudlak syndrome type 2), and LYST (Chediak-Higashi Syndrome)." (PMID 31396234, 2019). "Oxidative membrane damage resulting from aberrant LYST function could have particularly important ramifications for the neurodegenerative component of Chediak-Higashi syndrome." (PMID 20617205, 2010). "The extent to which Chediak-Higashi syndrome and exfoliation syndrome resemble each other at a mechanistic level remains to be determined, but both disease states clearly share important links to LYST." (PMID 20617205, 2010). "The genetic variants of LYST gene for Chediak-Higashi syndrome was no found." (PMID 40703525, 2025). "The LYST gene is mutated in autosomal recessive mode in inborn errors of immunity syndromes and, in particular, in familial hemophagocytic lymphohistiocytosis (FHL) syndromes with hypopigmentation: Chediak–Higashi syndrome and hemophagocytic lymphohistiocytosis (HLH)." (PMID 39118233, 2024). "LYST is involved in endolysosomal biogenesis, and defects in its coding region can result in enlarged lysosome-related organelles, including melanosomes, such as in the beige and gray phenotypes in mice, the Aleutian coloration in minks, and the Chédiak–Higashi syndrome in humans." (PMID 33020272, 2020). "Patients with autosomal recessive mutations in RAB27A and LYST, causative of Griscelli syndrome type 2 (GS2) and Chediak-Higashi syndrome (CHS), respectively, also frequently develop HLH." (PMID 26684649, 2015).
Chediak-Higashi syndrome (continued). "Since then, the study of familial cases allowed the recognition of genetic alterations directly affecting proteins involved in cytotoxic activity, such as Munc13-4 (FHL-3), Syntaxin 11 (FHL-4), Munc18-2 (FHL-5), RAB27A (Griscelli Syndrome type 2, GS2), LYST (Chediak-Higashi Syndrome, CHS)." (PMID 37426667, 2023). "Additionally, mutations in the HPS, CHS/LYST, MC1R, and OA1 genes have also been reported to cause different types of OCA through Hermansky-Pudlak syndrome (MIM# 203300), red-haired OCA2 (MIM#203200), Chediak–Higashi syndrome (MIM# 214500), and X-linked ocular albinism (MIM#300500), respectively." (PMID 35054407, 2021). "Defects in RAB27A, LYST, and AP3B1, leading to Griscelli syndrome type 2 (GS2), Chediak-Higashi syndrome (CHS), and Hermansky-Pudlak syndrome type 2 (HPS2), respectively, also cause defective degranulation." (PMID 31396234, 2019).
Immunodeficiency (12 papers, 2007 to 2025). Failure of the immune system to protect the body adequately from infection, due to the absence or insufficiency of some component process or substance. "Clinical features resulting from LYST mutations in CHS have much in common with immunodeficiencies caused by TLR signaling defects, such as conditions caused by autosomal recessive mutations in TLR adapters, IRAK-4 and MyD88 (OMIM# 610799, 607676, 612260)." (PMID 25528552, 2014). "In a separate cohort of 27 patients with inherited immunodeficiency disorders, 8 (29.6%) developed FHM associated with NHEJ1 or LYST variants, underscoring the familial clustering of hematologic disorders." (PMID 40047910, 2025).
chordoma (10 papers, 2017 to 2025). Chordomas are rare malignant tumors arising from embryonic remnants of the notochord in axial skeleton. "Our genomic data confirmed previous findings that PIK3CA and chromatin remodeling genes were among the most frequently mutated genes in chordoma, while the potential driver role of LYST and USP9X were less certain." (PMID 39135136, 2024). "Here, the frequency of tumours harbouring truncating LYST mutations was significantly enriched compared to 4947 non-chordoma tumours (p = 2.7 × 10−6; Fisher’s exact test; see ‘Methods’)." (PMID 29026114, 2017). "Functional genomics screens in chordoma cell lines with LYST loss may reveal targetable vulnerabilities created by this unique alteration." (PMID 36387127, 2022). "Given the apparent specificity of truncating LYST mutations to chordoma, they may have utility as an adjunct diagnostic tool." (PMID 29026114, 2017). "Intriguingly, one of the most frequently altered genes, mutated exclusively by inactivating mutation, was LYST (10%), which may represent a novel cancer gene in chordoma." (PMID 29026114, 2017). "LYST may work as a cancer gene in chordoma and prove to be an adjunct diagnostic marker." (PMID 36465398, 2022). "In summary, we identified candidate driver events (PBRM1+, SETD2+, CDKN2A/B+, TBXT/LYST+) in 33.75% (27 out of 80) of the skull-base chordoma patients we sequenced." (PMID 33536423, 2021). "Clearly, additional genomic studies and functional investigations are required to clarify the role of LYST in chordoma pathogenesis." (PMID 29026114, 2017). "Here, the authors investigate driver mutations of sporadic chordoma in 104 cases, revealing duplications in notochordal transcription factor brachyury (T), PI3K signalling mutations, and mutations in LYST, a potential novel cancer gene in chordoma." (PMID 29026114, 2017). "Although this proposition requires further validation, one may speculate on the biological role of LYST in chordoma development." (PMID 29026114, 2017). "We next considered that truncating LYST mutations may have accumulated as a consequence of hypermutation of the LYST locus in chordoma." (PMID 29026114, 2017). "The functional link of LYST to chordoma development may thus lie in aberrant function of notochordal lysosomes, potentially interfering with notochord cell differentiation." (PMID 29026114, 2017). "Our observation of non-random enrichment of truncating mutations in the LYST gene indicates that it may operate as a cancer gene in chordoma." (PMID 29026114, 2017). "The heatmap revealed that MIR5690, SNORD15B, RAB3B were highly expressed in chordoma, along with the generally reported chordoma regulators, such as KRT19, LYST, and EGFR." (PMID 40135815, 2025).
Griscelli syndrome type 2 (7 papers, 2012 to 2023). Griscelli syndrome type 2 (GS2) is a rare, inherited condition that affects the skin, hair, and immune system. "Identifiable causes include the following mutations: 9q21.3‐22, PRF‐1, UNC 13D, STX 11, and STX BP2, Chediak‐Higashi syndrome (CHS‐ 1/LYST), Griscelli syndrome type 2 (RAB 27A), Hermansky‐Pudlak syndrome type 2 (AP3B1), and the X‐linked lymphoproliferative syndromes XLP‐1 (SAP) and XPL‐2 (XIAP)." (PMID 35844997, 2020). "The following FHL subtypes have been described: FHL-2 due to mutations in PRF1, FHL-3 (UNC13D), FHL-4 (STX11), FHL-5 (STXBP2), Griscelli Syndrome type 2 (RAB27A) and Chediack-Higashi syndrome (LYST)." (PMID 37426667, 2023).